SIRPA (signal regulatory protein alpha)
Diseases named in the same sentence as SIRPA in open-access papers (continued):
Sharing a sentence is not in itself a finding about the gene and the disease.
tumor (continued). "NK cells typically targetvirally infected or tumor cells by recognizing down-regulated MHC molecules.Macrophages contribute to rejection through the loss of inhibitory interactionbetween signal regulatory protein alpha (SIRPa) on macrophages and CD47 on porcine cells." (PMID 39139422, 2024). "In addition, blocking the CD47/SIRPα axis can induce M1 polarization in tumor-associated macrophages and increase macrophage recruitment, and can promote phagocytosis by DSs and consequent antigen presentation to CD8+ T-cells, inducing an adaptive anti-tumor immune response." (PMID 37371818, 2023). "Additionally, the inhibition of CD47, a ligand for the macrophage-associated signal-regulatory protein α (SIRPα) has been shown to increase phagocytosis of EC tumor cells by TAMs, although CD47- SIRPα pathway inhibition has not yet been considered for clinical trial." (PMID 36072799, 2022). "However, anti-SIRPα antibodies cause tumor cell phagocytosis while preserving T-cells." (PMID 36303138, 2022). "However, doxorubicin treatment of mice increased SIRPα expression in tumor-associated macrophages, suggesting that secreted soluble factors from macrophage-surrounding cells in tumor microenvironment enhance SIRPα expression." (PMID 36274066, 2022). "Indeed, a variant of CD47 with improved affinity for SIRPα had a synergistic effect when used in combination with tumor-specific monoclonal Abs to ameliorate phagocytosis of tumor cells in vitro, although its antitumoral effects in vivo have not been evaluated." (PMID 31921125, 2019). "Validation of a radiolabeled lead candidate, further referred as [64Cu]copper-SIRPα-nanobody ([64Cu]Cu-SIRPα-Nb), demonstrated its suitability for monitoring the dynamics of myeloid cells in a preclinical tumor mouse model." (PMID 40876955, 2026). "In macrophages, phosphorylated SIRPα dampens proinflammatory responses and facilitates tumor immune evasion, whereas its inhibition enhances ROS production, antigen presentation, and antitumor immunity." (PMID 41486149, 2026). "Additional strategies, including oncolytic viruses and macrophage-specific checkpoint blockade (e.g., CD47/SIRPα axis inhibitors), simultaneously promote tumor clearance and immune activation." (PMID 41924264, 2026). "Immunofluorescence confirmed higher abundance of SIRPA+ macrophages within tumor parenchyma and their spatial colocalization with GSC markers." (PMID 42116089, 2026). "GMI inhibited STAT3, reduced macrophage M2 polarization and SIRPα levels and enhanced their immune and anti-tumour functions." (PMID 41438583, 2026). "Second, approximately 75% of the patients received neoadjuvant treatment in this study; therefore, potentially altering the tumor immune microenvironment and affecting the expression levels of SIRPα and CD47." (PMID 40926176, 2026). "This comprehensive computational approach yields critical structural insights into the interaction between macrophage SIRPα and the tumor cell CD47 immune checkpoint, elucidating the role of αvβ3 in stabilizing CD47 distribution on the cell membrane." (PMID 41168993, 2026). "We performed IHC staining to evaluate the expression of CD47 and SIRPα in resected tumor tissues from 100 patients who underwent esophagectomy for ESCC." (PMID 40926176, 2026). "In the 4MOSC1 syngeneic HPV-negative HNSCC mouse model, ALX301 (an engineered CD47-blocking SIRPα fusion for murine models) induced complete tumor regression when combined with anti-PD-1, and produced a partial tumor response as a monotherapy." (PMID 41701713, 2026). "CD47 is a transmembrane protein overexpressed in hematological malignancies and represents an innate immune checkpoint as it binds to its receptor SIRPα on macrophages inhibiting phagocytosis and favoring the immune evasion of tumor cells." (PMID 40369208, 2025).
tumor (continued). "In this study, we constructed an oncolytic adenovirus designed to express an engineered SIRPα variant with an IgG1 Fc protein and investigated its therapeutic efficacy against CD47+ murine tumor cell lines both in vitro and in vivo." (PMID 40070841, 2025). "CD47, expressed on the surface of tumor cells, binds signal regulatory protein α (SIRPα) on macrophages, preventing macrophage-mediated tumor clearance through phagocytosis." (PMID 40607438, 2025). "In other words, for medium-sized tumors (100 to 400 mm3), given the same irradiation dose, CD47-KO is more effective in reducing the tumor than SIRPα-KO and anti-SIRPα, which in turn is more effective than anti-CD47." (PMID 41296731, 2025). "This initial observation laid the groundwork for our subsequent inquiry into the functionality and efficacy of the SIRPα mutant secreted by tumor cells infected with the engineered oAd-SA." (PMID 40070841, 2025). "CD47, an innate immune checkpoint frequently overexpressed in CRC, serves as a major “don’t eat me” signal, by binding to SIRPα on the surface of macrophages, thereby inhibiting phagocytosis and facilitating tumor immune evasion." (PMID 41514569, 2025). "We found that anti-SIRPα therapy effectively blocked the SIRPα expression in CD45+CD11b+ TIMs in the tumor." (PMID 40523887, 2025). "As a small molecule inhibitor, RRx-001 can polarize the low phagocytic M2 phenotype of tumor-associated macrophages to a high phagocytic M1 phenotype, and can decrease the levels of CD47 on cancer cells and SIRPα on macrophages simultaneously." (PMID 40548122, 2025). "In a series of in vivo experiments, we demonstrated the anti-tumor and immune-active effect of SIRPα-blocked therapy." (PMID 40523887, 2025). "CD47 contributes to tumor immune escape by binding to signal regulatory protein alpha (SIRPα) on myeloid cells, delivering a “don’t eat me” signal that prevents tumor cell phagocytosis by macrophages." (PMID 41295262, 2025). "Further analysis revealed that immune checkpoint genes CD47, PVR, SIRPA, and VTCN1 were found to be elevated in the high-risk cohort, indicating their role in suppressing anti-tumor immunity." (PMID 40243557, 2025). "To elucidate the mechanism behind the superior tumor control observed in the RT and SIRPα blockade combination, we used flow cytometry to measure SIRPα, CD209, and HLA-DR expression in tumor tissues from the xenograft models." (PMID 40208335, 2025). "We next examined the PD-L1 expression and PI3K/AKT signaling activation in macrophages and G-MDSCs in these tumor tissues, and found that compared with the control group, anti-SIRPα treatment downregulated p-AKT and PD-L1 expression in myeloid cells." (PMID 40523887, 2025). "CD47/SIRPα blockade disrupts the “don’t eat me” signal, enabling macrophages to phagocytose tumor cells." (PMID 40643516, 2025). "Developing bispecific antibodies that combine anti-SIRPα mAbs with tumor opsonizing mAbs, such as anti-EGFR, represents a promising approach." (PMID 40136470, 2025). "Multiple anti-SIRPα antibodies developed for solid tumor treatment in preclinical studies have demonstrated significant efficacy in suppressing tumor progression." (PMID 40589735, 2025). "These include signal regulatory protein α (SIRPA), which showed significantly higher expression in tumor tissues versus paracancerous/normal tissues." (PMID 41450739, 2025). "Nevertheless, inhibition of CD47/SIRPα interaction monotherapy is insufficient to control tumor progression in some cancers which will require combination treatment to achieve synergistic effects." (PMID 40070841, 2025). "Through in vivo experiments, we showed that anti-SIRPα therapy inhibited tumor growth, accompanied by increased CD8+ T cells infiltration and decreased TIMs including MDSCs and macrophages." (PMID 40523887, 2025).
tumor (continued). "Mechanistically, the binding between CD47 on tumor cells and SIRPα on DCs and macrophages mitigates phagocytosis activities of DCs and macrophages and further dampen their antigen presentation activity to result in tumor immune evasion." (PMID 40908470, 2025). "Repolarizing immunosuppressive M2-phenotype tumor-associated macrophages (TAMs) and blocking the CD47/SIRPα axis are promising strategies to enhance cancer immunotherapy." (PMID 42039278, 2025). "Targeted editing of key nodes—including MerTK, CD47, and SIRPα—enhances phagocytic capacity and potentiates antitumor immunity in preclinical tumor models." (PMID 41403915, 2025). "Another study also suggested that radiotherapy combined with SIRPα and PD-1 blockade significantly promoted systemic tumor regressions." (PMID 40523887, 2025). "CD47 is widely expressed in normal human cells; however, SIRPα/CD47 blockade primarily results in tumor cell phagocytosis, as normal human cells lack pro-phagocytic signals." (PMID 41171165, 2025). "SIRPα−/− mice exhibit a significantly slower tumor growth rate with a smaller engraftment at 5×103 cells/mouse." (PMID 41296731, 2025). "Cluster of differentiation 47 (CD47) delivers an inhibitory signal that suppresses phagocytosis and prevents immune clearance of tumor cells by interacting with signal regulatory protein alpha (SIRPα) on myeloid cells." (PMID 41131565, 2025). "Block the CD47 ‐ SIRPα signaling pathway and increase the activity of phagocytes to enhance phagocytosis of tumor cells." (PMID 40657202, 2025). "Further studies are warranted to dissect the cell type-specific functions of SIRPα across immune subsets and tumor cells, which will inform the development of precision immunotherapies tailored to distinct immunological and oncogenic contexts." (PMID 40589735, 2025). "Contrastingly, tumor-intrinsic SIRPα primarily influences malignant phenotypes—such as proliferation, migration, and invasion—via direct intracellular signaling pathways." (PMID 40589735, 2025). "Recent studies reveal that CD47 can interact with its receptor, signal-regulatory protein alpha (SIRPα), on phagocytic cells like macrophages and dendritic cells to inhibit their ability to engulf cancer cells, promoting immune evasion and tumor growth." (PMID 39781344, 2025). "Radiotherapy-induced effects are mainly related to radioresistance by upregulation of CD47 or SIRPα, but other studies demonstrated that it can also induce tumor cells sensitivity to radiotherapy by inhibiting CD47 expression." (PMID 40835598, 2025). "This interaction is further confirmed by immunohistochemical (IHC) analysis, which revealed that CD47+ tumor cells locate in proximity to SIRPA+ macrophages." (PMID 41450739, 2025). "CD47/SIRPα blockade is expected to enhance the phagocytic activity of TAMs against cancer cells and exert effective anti-tumor activity." (PMID 40508145, 2025). "CD47 functions by inhibiting macrophage phagocytosis of tumor cells through its binding to signal regulatory protein α (SIRPα) on the surface of macrophages, thereby promoting tumor growth and metastasis." (PMID 39781344, 2025). "The combination of RT and anti-SIRPα showed superior tumor control compared to anti-PD1, which is potentially due to the enhanced antigen presentation capacity of SIRPα + CD209 + cells." (PMID 40208335, 2025). "CD47, often overexpressed on tumor cells, serves as a “don’t eat me” signal by engaging SIRPα on macrophages to suppress phagocytosis." (PMID 40800581, 2025). "After SIRPα-KO, neutrophils polarize toward the anti-tumor N1 phenotype, with enhanced phagocytic function and reduced inflammatory cytokine secretion, thereby inhibiting the growth of lung cancer." (PMID 40589735, 2025). "KWAR23, an anti-SIRPα antibody, significantly enhances the antitumor activity of neutrophils and macrophages when paired with tumor-opsonizing antibodies and is in clinical testing." (PMID 40070841, 2025).
tumor (continued). "A further investigation identified as a tumor cell CD47 binding to APC surface SIRPα as a potential mechanism suppressing phagocytic activity, offering initial insights into CM’s immune escape strategy." (PMID 40959090, 2025). "Emerging next-generation strategies, such as SIRPα-directed agents, bispecific antibodies, and conditionally active therapeutics, are designed to enhance safety and tumor selectivity and reduce systemic toxicity." (PMID 41179296, 2025). "For example, the CD47/SIRPα axis was identified in the late 1990s as the first tumor phagocytosis checkpoint." (PMID 40835598, 2025). "The collective findings from these assays converge to suggest that the SIRPα mutant released by oAd-SA-infected tumor cells not only retains its functionality but also exerts a potent effect on modulating the tumor-immune cell interaction." (PMID 40070841, 2025). "Macrophage-targeted checkpoint inhibitors, including SIRPα inhibitors (which block the tumor CD47 “don’t eat me” signal), are being evaluated in OC." (PMID 40643516, 2025). "For example, The “Do not eat me” signal formed by the binding of the CD47 protein, which is expressed on the tumor cells, to signal-regulatory protein alpha (SIRPα), which is expressed on myeloid cells, enables tumor cells to evade immune surveillance." (PMID 40461514, 2025). "Another justification stems from pairing PARPi with anti-CD47 or anti-SIRPα therapies to reduce phagocytic thresholds and drive the additional myeloid presence towards effective tumor elimination and cross-priming of T cells." (PMID 41488638, 2025). "Targeting CD47 or its receptor SIRPα has emerged as a promising therapeutic strategy to enhance anti-tumor immunity." (PMID 40655153, 2025). "Reciprocally, HDACi-upregulated CD47 polarized macrophages towards a pro-tumor M2 phenotype through SIRPα ligation." (PMID 39994810, 2025). "CD47 enhances the ability of tumor cells to evade macrophage phagocytosis by participating in SIRPα." (PMID 40548122, 2025). "Binding to SIRPα delivers “don’t eat me” signal that inhibits phagocytosis, thereby allowing tumor cells to evade immune clearance." (PMID 40529368, 2025). "SIRPα-blockade therapy reversed the immunosuppressive TME through inhibiting the pro-tumor polarization of PD-L1+ TIMs." (PMID 40523887, 2025). "Collectively, myeloid-intrinsic SIRPα modulates the tumor immune microenvironment by regulating the immunomodulatory functions of macrophages, neutrophils, and DCs." (PMID 40589735, 2025). "Above all, these findings suggested that anti-SIRPα treatment suppressed pro-tumor characteristics of M2-like macrophages and G-MDSCs in vitro." (PMID 40523887, 2025). "The binding of CD47 to SIRPα on macrophages sends a “don't eat me” signal, thereby suppressing the phagocytic activity of these immune cells and allowing tumor cells to evade immune response." (PMID 40385528, 2025). "This interaction between CD47 and SIRPα attenuates the phagocytic activity of macrophages, enabling tumor cells to obviate destruction." (PMID 40607254, 2025). "In SIRPα−/− mice, immune activation due to the same irradiation dose (8 Gy) is higher for KPC tumor than Pan02 and MC38 tumors, suggesting that KPC cells can be more susceptible to SIRPα-based treatment under RT." (PMID 41296731, 2025). "It binds with SIRPα on innate immune cells, which triggers “don’t-eat-me” signaling, ultimately leading to tumor immune evasion." (PMID 41511303, 2025). "Blockade of the CD47/SIRPα axis enhances macrophage-dependent phagocytosis of tumor cells, establishing this immune checkpoint as a therapeutic target in cancer immunotherapy." (PMID 40578556, 2025). "This is consistent with known SIRPα expression on neutrophils and their ability to kill tumor cells following CD47/SIRPα blockade." (PMID 41171165, 2025). "Beyond phagocytosis-related antitumor immune response, the anti-CD47/SIRPα axis also enhances tumor cells sensitivity to radiotherapy through phagocytosis-independent mechanisms." (PMID 40835598, 2025).
tumor (continued). "Collectively, these data suggested that SIRPα blockade therapy inhibited tumor growth and infiltration of TIMs while upregulating infiltration and cytotoxic function of CD8+ T cells." (PMID 40523887, 2025). "It was found that SHP2 deneddylation, through the CD47/SIRPα axis, mediated tumor immune suppression in colon cancer, and the administration of allosteric SHP2 inhibitors sensitized immunotherapy-resistant colorectal cancer to immunotherapy." (PMID 40861801, 2025). "Here, we found that anti-SIRPα therapy significantly inhibited tumor growth through hampering the immunosuppressive TME in mouse." (PMID 40523887, 2025). "CD47 is often upregulated in tumor cells, where it interacts with SIRPα on surfaces of macrophages, to release the self-recognition signal, and thereby evading CAR-Ms phagocytic activity." (PMID 40814015, 2025). "Targeted blockade of the interaction between CD47 and SIRPα can potentially enhance the phagocytic activity of macrophages against tumor cells, thereby promoting the body’s immune response to the tumor." (PMID 41341383, 2025). "More critically, CD47 interaction with SIRPα on myeloid cells initiates a “don’t-eat-me” signal that enables tumor cells to evade phagocytosis by macrophages and neutrophils." (PMID 40948940, 2025). "To delineate the underlying mechanism whereby anti-SIRPα inhibited HCC progression in TME, we established a spontaneous tumor model and used anti-SIRPα mAb to treat the tumor." (PMID 40523887, 2025). "Our data also suggested that anti-SIRPα antibody significantly inhibited tumor growth in the subcutaneous tumor model." (PMID 40523887, 2025). "The sensitivity analysis of LQ model parameters in WT and SIRPα−/− mice, focusing on different tumor sizes, reveals that these RT parameters have minimal impact on tumor response in WT mice, while a more pronounced effect is observed in SIRPα−/− mice." (PMID 41296731, 2025). "It engages with signal regulatory protein α (SIRPα) on macrophages, which inhibits their phagocytosis of normal cells and, in turn, aids tumor cells in evading the immune system." (PMID 40487639, 2025). "Multiple antibodies targeting CD47 have been developed to prevent SIRPα activation and reprogram TAMs for tumor cell phagocytosis." (PMID 41417432, 2025). "A pivotal mechanism of immune evasion is orchestrated by the CD47-SIRPα axis, whereby tumor cells upregulate the "don't eat me" signal CD47 to engage the inhibitory receptor SIRPα on tumor-associated Mφs (TAMs) and suppress phagocytosis." (PMID 41164198, 2025). "OAd-SIRPα-Fc and OAd-Siglec10-Fc have been shown to significantly suppress tumor growth in macrophage-rich tumor microenvironments, while OAd-TIGIT-Fc primarily enhances T cell activation." (PMID 40698086, 2025). "The “don’t eat me” signal is released by CD47 in conjunction with its receptor, SIRPα, on macrophages, which weakens macrophage phagocytosis, thereby facilitating tumor cell escape from immune surveillance and clearance." (PMID 40051791, 2025). "The interaction between CD47 on tumor cells and signal regulatory protein alpha (SIRPα) on phagocytes delivers an antiphagocytic signal." (PMID 41488615, 2025). "Blockade of the CD47/SIRPa axis has emerged as a promising approach to enhance macrophage-mediated anti-tumor activities in cancer immunotherapy." (PMID 41383500, 2025). "Knockdown of SIRPα induces the upregulation of p27, subsequently inhibiting cell cycle progression and reducing tumor growth." (PMID 40589735, 2025). "Hematological malignancies express high levels of CD47 as interactions between CD47 on cancer cells and SIRPα on macrophages inhibit phagocytosis resulting, thus, in tumor immune evasion." (PMID 40369208, 2025). "In hepatocellular carcinoma cells, SIRPα has been shown to negatively regulate tumor initiation, primarily through the inhibition of the ERK and NF-κB pathways." (PMID 40589735, 2025).